TAF1 (TATA-box binding protein associated factor 1)
Diseases named in the same sentence as TAF1 in open-access papers (continued):
Sharing a sentence is not in itself a finding about the gene and the disease.
cancer (25 papers, 2013 to 2025). A tumor composed of atypical neoplastic, often pleomorphic cells that invade other tissues. "Particularly, the genes that showed the highest mutation frequency across all cancers overall were TAF1, NFX1, and RNF10." (PMID 40591126, 2025). "Multiple TAFs have been shown to be mutated or dysregulated in cancer, including TAF1, TAF2, TAF4/TAF4B, TAF6, TAF9, TAF10 and TAF12." (PMID 39323550, 2024). "Variants of the gene or disrupted expression are implicated in neurodevelopment but mutated variants of TAF1 have also been implicated in cancer." (PMID 34941772, 2021). "The cBioPortal and catalog of somatic mutations in cancer (COSMIC) databases denote several mutations in the conserved CCHC residues of TAF1 including: C1285R, C1288R, H1293N, C1300W/R." (PMID 29545534, 2018). "The SNV heatmap showed that mainly TAF1 had a high SNV mutation frequency across some cancer types." (PMID 40591126, 2025). "TAF1 has also been linked to tumorigenesis, and we speculate it might be differentially regulated by cancer cells as evidenced in multiple types of cancers." (PMID 39323550, 2024). "Therefore, we linked the 10 candidate repurposable drugs with TAF1 (hub protein) as a novel therapeutic strategy for cancer treatment." (PMID 39765756, 2024). "Additionally, there may be a relationship between CNOT4 in LIHC cancer, and TAF1 may be associated with SARC cancer." (PMID 40591126, 2025). "A characteristic of cancer cells is an evasion of apoptosis and TAF1 has been linked to the regulation of oxidative and genotoxic stress-induced apoptosis through control of p27Kip1 expression indicating that TAF1 inhibition may be oncogenic in some cases." (PMID 39323550, 2024). "TATA-box-binding protein (TBP)-associated factor 1 (TAF1) is a key component of RNA polymerase II and is known to play a critical role in the regulation of cell growth and the cell cycle, whereas its role in cancer development is largely unknown." (PMID 38045002, 2023). "Further we also identify key master cancer regulators like SMAD4, EP300, KAT6A and TAF1 which are associated with multiple cancers and are related to critical oncogenic processes." (PMID 41404623, 2025). "To date, only several studies have analyzed the roles of TAF1 or TAF1L in facilitating cancer development and progression." (PMID 36674511, 2023). "In cancer researches, although it has known that TAF1 can play important roles on cell proliferation and apoptosis 11, little is known in regards to that is pathophysiological functions of TAF1L." (PMID 32174793, 2020). "The mechanism for MIAT to exert chemoresistance to cancer cells is that MIAT can recruit a transcription factor, TATA-box binding protein-associated Factor 1 (TAF1), in the promoter region of sterol regulatory element binding transcription factor 1 (SREBF1) and enhance the expression of SREBF1." (PMID 40781643, 2025). "However, reference compounds and in vitro cell viability and cytotoxicity assays in cancer cell lines demonstrated superior effects of high affinity tyrosine kinase inhibition compared to inhibition of the TAF1 bromodomain." (PMID 40153395, 2025). "By novelly targeting both FLT3 kinase and the TAF1 bromodomain, we anticipated that these novel agents may have a lower propensity to result in drug-resistant cancers." (PMID 40153395, 2025). "Additionally, it is possible that even following inhibition of both bromodomains, other functions of TAF1 are sufficient to maintain cancer cell proliferation." (PMID 40153395, 2025). "We assumed that simultaneously targeting both FLT3 kinase and TAF1-bromodomains may potentially have a lower propensity to result in drug-resistant cancers." (PMID 40153395, 2025). "TAF1L is also dysregulated in a number of cancers, indicating that it may have a similar function to TAF1 in the regulation of tumorigenesis." (PMID 39323550, 2024). "Thus, TAF1 is likely to play roles in a variety of cancers although mechanisms are yet to be elucidated." (PMID 39323550, 2024).
cancer (continued). "This analysis found that, compared to NATs, cancer cells can in general tolerate to a greater degree the genomic deletion of KATs compared to NATs, with a small fraction of highly essential enzymes (e.g., TAF1 and ELP3)." (PMID 32942614, 2020). "When taken together with the highly penetrant Rb synthetic lethal interaction, this might make TAF1 an attractive target for cancer drug discovery." (PMID 29915391, 2018). "Thus, TAF1 may be differentially expressed in clinical conditions such as cancer and there may be cell type-specific roles of TAF1 and its isoforms." (PMID 39323550, 2024). "Notably, targeting TAF1 has emerged as a therapeutic approach in various cancers." (PMID 39765756, 2024). "Although the significance of the TAF1/1L mutations is not known, the frequency of mutations suggest that TAF1/1L may play some functional role in modulating the phenotype of cancer cells." (PMID 23390603, 2013). "Although this study provides a pan-cancer map of putative TF regulators, the prognostic and mechanistic relevance of central hubs, particularly MYC, TAF1, and EGR1, requires validation in future studies using independent, cancer type–specific cohorts such as those available from TCGA." (PMID 41155227, 2025). "Overall, the majority of studies, albeit limited, indicate that TAF1 has a pro-tumorigenic rather than a tumour-suppressive function in cancer." (PMID 39323550, 2024). "The notably high overlapping ratios were discerned for TFs playing critical roles in transcription pre-initiation or RNA polymerase activities, e.g., UBTF, TAF1, and POLR2A, in addition to others, like E2F6, IRF1, and MYC, which are involved in cancer-related processes." (PMID 36092921, 2022). "Given the close homology between TAF1 and TAF1L, it was hypothesized that TAF1L may have similar regulatory functions in cancer." (PMID 34771455, 2021). "AE/TAF1 co-bound peaks at non-TSS are adjacent to genes involved in pathways in cancer and AML while AE unique peaks at non-TSS regions are not directly involved in these pathways implying the importance of the TAF1/AE complex in these pathways." (PMID 31664040, 2019). "Next generation sequencing analysis with “Comprehensive Cancer Panel” highlighted the presence of multiple non-targetable mutations in the FLT4, UBR5, ATM, TAF1, and GUCY1A2 genes." (PMID 30172261, 2018). "In this study, TAF1 was proposed as a promising target for SNSCC therapy due to its (i) central role as an upregulated hub protein in SNSCC, (ii) involvement in transcriptional and histone modification, and (iii) overexpression in several cancer types, as revealed by a literature review." (PMID 39765756, 2024). "Post-treatment samples may also acquire mutations in known cancer driver genes (for example, SF3B1, TAF1 and CCND2) that are absent from the paired pre-treatment sample." (PMID 27045317, 2016). "NGS analyses with Comprehensive Cancer Panel highlighted the presence of multiple non-targetable mutations in fms-related tyrosine kinase 4 (FLT4), ubiquitin-protein ligase E3 component N-recognin 5 (UBR5), ataxia telangiectasia mutated (ATM), and TATA-box binding protein associated factor 1 (TAF1)." (PMID 30172261, 2018). "In addition, therapeutic approaches aimed at disrupting key regulatory interactions, including those involving TAF1, MYC, MAZ, and other TFs such as KLF15 and ZNF281, may suppress tumor growth and modulate stress adaptation, thereby enabling more precise interventions against cancer." (PMID 41155227, 2025). "In addition, TAF1 and AE shared binding sites at non-TSS are close to the genes involved in cancer or AML pathways, while the AE unique peaks (which are not overlapping with TAF1) at non-TSS are not directly related to these pathways." (PMID 31664040, 2019).
cancer (continued). "In addition to these five TFs, we identified BATF, SMARCB1, TAF1 and MXI1 as novel TERT regulators across cancer entities that to our knowledge, so far, have not been described in the literature as TERT regulators." (PMID 31888467, 2019).
tumor (15 papers, 2013 to 2026). "In uterine serous carcinoma, seven TAF1 mutations were identified in unmatched tumours, most of which lay in the TAF7-interacting region, but the functional outcome of these mutations was not investigated." (PMID 39323550, 2024). "TAF1_5496_1732 disrupts TAF1, a key transcriptional regulator implicated in cell cycle progression and tumor maintenance, suggesting that transcriptional regulatory mechanisms may be a therapeutic target in low-risk tumors." (PMID 40959429, 2025). "In contrast, under expression of TAF1, often modulated by microRNAs, reduces the activity of tumor suppressor genes, creating a tumor-friendly environment." (PMID 41155227, 2025). "Given its capacity to indirectly alter tumor adaptability, TAF1 might be seen as an ideal example of a goner." (PMID 41155227, 2025). "Interaction between retinoblastoma protein Rb and TAF1 inhibits its kinase activity, which suggests that TAF1 may play a role in tumor suppression." (PMID 35625613, 2022). "In the tumor “top100” list, TAF1 and HNF4A are the main hub genes." (PMID 35428183, 2022). "Knockdown of TAF1 in SCLC cells restored MHC-I expression, suppressed tumor growth in immunocompetent mice, and increased CD8+ T cell infiltration." (PMID 42193300, 2026). "Although the specific function of the two separate bromodomains BD1 and BD2 of transcription initiation factor TFIID subunit 1 (TAF1) remains ambiguous, they are recognized as potential targets for tumor therapy." (PMID 37142850, 2023). "It has been reported that a combination of TAF1 and BRD4 inhibitors offered synergistic anti-proliferative effects in tumor cells." (PMID 37142850, 2023). "Nude mice were injected with lncRNA altered FOXD2‐AS1 and silenced TAF‐1 GSCs, and RT‐qPCR was then used to determine lncRNA FOXD2‐AS1 and TAF‐1 expression levels in tumours from the mice." (PMID 35419917, 2022). "Therefore, TAF1 is a hub gene in both the normal and tumor lists, while HNF4A, MAX, and MYC are not." (PMID 35428183, 2022).
neurodevelopmental disorder (5 papers, 2017 to 2024). A behavioral and cognitive disorder with onset during the developmental period that involves impaired or aberrant development of intellectual, motor, or social functions. "Variants of TAF1 have been associated with neurodevelopmental disorders, but TAF1’s molecular functions remain elusive." (PMID 31341187, 2019). "Variants of TAF1 are associated with neurodevelopmental disorders." (PMID 33359140, 2021).
neurological disease (5 papers, 2007 to 2024). "Although skewed X‐chromosome inactivation has been reported as the underlying mechanism in at least 1 case of an XDP‐carrier symptomatic female, it has also been shown to be the underlying protective mechanism against X‐linked neurological diseases caused by TAF1 coding mutations." (PMID 32975318, 2021). "As this is a neurological disease, we studied the brains of Taf1 1loxP heterozygous females for gross structural abnormalities, overall expression by quantification of TAF1 mRNA and protein, and cellular localisation of the protein." (PMID 38804708, 2024). "In conclusion, our findings imply that the T-type calcium channels are novel molecular targets to develop therapeutics to treat TAF1 ID syndrome and that SAK3 is an attractive drug candidate to treat TAF1 associated neurological disorders." (PMID 33359140, 2021). "Moreover, XDP might not be the only link between TAF1 and neurologic disease." (PMID 26769797, 2016).
neurodegenerative disease (4 papers, 2020 to 2024). A disorder of the central nervous system characterized by gradual and progressive loss of neural tissue and neurologic function. "X-linked dystonia parkinsonism (XDP) is an inherited neurodegenerative disease in which a SINE-VNTR-Alu (SVA) retrotransposon, characterised by amplification of a G-rich repeat, is inserted into the coding sequence of TAF1, a key partner of RNA polymerase II." (PMID 39287133, 2024). "Finally, and most critically, this mouse will be a platform for the advancement of therapeutics for TAF1 neurodevelopmental and neurodegenerative disease." (PMID 38804708, 2024).
infection (2 papers, 2011 to 2019). The state of being infected such as from the introduction of a foreign agent such as serum, vaccine, antigenic substance or organism. "TAF7 was recently demonstrated to also regulate the acetyl transferase activity of CIITA, which is the key factor in TAF1-independent transcription of MHC class I and II in response to infection." (PMID 22043290, 2011).
genetic diseases (1 paper, 2018). "Bioinformatics analysis suggests that TAF1 is a part of a 72-gene network involved in early brain development, and when mutated frequently causes genetic diseases." (PMID 32714589, 2018). "As such, further investigation of this rare genetic disease is greatly needed, and the development of an animal of TAF1-ID syndrome is warranted." (PMID 32714589, 2018).
psychiatric disorder (1 paper, 2017). A disorder characterized by behavioral and/or psychological abnormalities, often accompanied by physical symptoms. "We also identified specific TFBSs enriched in psychiatric disorder meQTL targets such as TAF1 and STAT1." (PMID 29066808, 2017).
TAF1 also shares sentences with these, for which no sentence is quoted: autism (2 papers); developmental delay (2); movement disorder (2); non-small cell lung carcinoma (2); Adult onset (1); amyotrophic lateral sclerosis (1); Arboleda-Tham syndrome (1); bipolar disorder (1); colon adenocarcinoma (1); depressive disorder (1); encephalitis (1); gastric cancer (1); lung adenocarcinoma (1); lung squamous cell carcinoma (1); lymph node metastasis (1); major depressive disorder (1); microcephaly (1); neural tube defect (1); neuroleptic malignant syndrome (1); Obesity (1); ovarian endometrioid adenocarcinoma (1); peripheral neuropathies (1); sexual (1); small cell lung carcinoma (1); uterine cancer (1).